ISL1 (ISL LIM homeobox 1)
Description:
DNA-binding transcriptional activator. Recognizes and binds to the consensus octamer binding site 5'-ATAATTAA-3' in promoter of target genes. Plays a fundamental role in the gene regulatory network essential for retinal ganglion cell (RGC) differentiation. Cooperates with the transcription factor POU4F2 to achieve maximal levels of expression of RGC target genes and RGC fate specification in the developing retina. Involved in the specification of motor neurons in cooperation with LHX3 and LDB1 (By similarity). Binds to insulin gene enhancer sequences (By similarity). Essential for heart development. Marker of one progenitor cell population that give rise to the outflow tract, right ventricle, a subset of left ventricular cells, and a large number of atrial cells as well, its function is required for these progenitors to contribute to the heart. Controls the expression of FGF and BMP growth factors in this cell population and is required for proliferation and survival of cells within pharyngeal foregut endoderm and adjacent splanchnic mesoderm as well as for migration of cardiac progenitors into the heart (By similarity).
Synonyms: Isl-1; ISLET1
Tractability: PROTAC: UniProt records ubiquitination sites on it; ubiquitination databases record sites on it.
Gene: Protein-coding gene on chromosome 5 (51,383,443 to 51,394,730, forward strand). Ensembl gene ENSG00000016082.
Subcellular location: Nucleus
Subcellular location (Human Protein Atlas): Nucleoplasm; Mitochondria; Nuclear speckles
Pathways (Reactome):
Developmental Biology: Cardiogenesis; Regulation of expression of SLITs and ROBOs
Metabolism of proteins: Synthesis, secretion, and inactivation of Glucose-dependent Insulinotropic Polypeptide (GIP)
Gene Ontology:
Molecular function: bHLH transcription factor binding; DNA-binding transcription activator activity, RNA polymerase II-specific; protein binding; RNA polymerase II cis-regulatory region sequence-specific DNA binding; RNA polymerase II-specific DNA-binding transcription factor binding; sequence-specific double-stranded DNA binding; cis-regulatory region sequence-specific DNA binding; DNA-binding transcription factor activity, RNA polymerase II-specific; nuclear estrogen receptor binding; nuclear receptor binding; promoter-specific chromatin binding; chromatin binding; core promoter sequence-specific DNA binding; DNA binding; LIM domain binding; sequence-specific DNA binding; transcription cis-regulatory region binding
Biological process: cardiac cell fate determination; positive regulation of insulin secretion; positive regulation of transcription by RNA polymerase II; secondary heart field specification; atrial septum morphogenesis; axonogenesis; cardiac right ventricle morphogenesis; cellular response to glucocorticoid stimulus; endocardial cushion morphogenesis; heart development; innervation; mesenchymal cell differentiation; negative regulation of inflammatory response; negative regulation of intracellular estrogen receptor signaling pathway; negative regulation of neuron apoptotic process; negative regulation of protein-containing complex assembly; negative regulation of transcription by RNA polymerase II; neuron fate specification; outflow tract morphogenesis; outflow tract septum morphogenesis; pancreas development; peripheral nervous system neuron axonogenesis; pharyngeal system development; positive regulation of angiogenesis; positive regulation of cell differentiation; and 26 more
Cellular component: chromatin; cytoplasm; nucleus; transcription regulator complex
Genetic constraint (gnomAD): Loss-of-function variants: 3 observed, 33.06 expected, observed/expected ratio (o/e) 0.0907, 90% interval 0.04 to 0.23. The upper end of that interval is the gene's LOEUF score, 0.23, which puts it in group 1 of 6, group 1 being the genes least tolerant of losing a copy. Missense variants: 293 observed, 447.43 expected, observed/expected ratio (o/e) 0.65, 90% interval 0.59 to 0.72. Synonymous variants: 170 observed, 166.56 expected, observed/expected ratio (o/e) 1.02, 90% interval 0.9 to 1.16.
Gene-disease validity (ClinGen):
ClinGen rates the evidence that ISL1 causes each of these diseases.
congenital heart disease (autosomal dominant): Definitive. A heart disease that is present at birth.
Homologues: Orthologues: chimpanzee ISL1 (100% identical), dog ISL1 (100% identical), guinea pig ISL1 (100% identical), mouse Isl1 (100% identical), pig ISL1 (100% identical), rabbit ISL1 (100% identical), rat Isl1 (100% identical), zebrafish isl1a (98% identical), tropical clawed frog isl1 (95% identical), macaque ISL1 (81% identical), Drosophila melanogaster tup (62% identical), Caenorhabditis elegans lim-7 (41% identical). Paralogues in human: ISL2 (76% identical).
Diseases named in the same sentence as ISL1 in open-access papers:
ISL1 is named in the same sentence as 141 diseases in open-access papers, as found by Europe PMC text mining. Sharing a sentence is not in itself a finding about the gene and the disease. The quoted sentences say what the papers report.
neuroblastoma (17 papers, 2018 to 2025). Neuroblastoma (NB) is the most common solid, extracranial childhood tumor. "Taken together, our study uncovered a temporal requirement for ISL1 during sympathetic neurogenesis, and implicated Isl1 as a candidate gene for neuroblastoma." (PMID 29445148, 2018). "ISL1 regulates directly or indirectly a number of genes essential for sympathetic neuron proliferation and differentiation, many of which have been implicated in neuroblastoma pathogenesis, suggesting Isl1 as a candidate gene for neuroblastoma." (PMID 29445148, 2018). "A number of genes implicated in neuroblastoma pathogenesis are direct downstream targets of ISL1." (PMID 29445148, 2018). "In neuroblastoma, our analysis identified the transcription factors ISL1, HAND2, PHOX2B, PHOX2A, and MYCN as the top five targets critical for the survival of cell lines." (PMID 37297004, 2023). "These include increased dependencies on ISL1, GATA3, and MYCN in neuroblastoma, all of which were recently reported as part of the core regulatory circuitry (CRC) in neuroblastoma and associated with superenhancers." (PMID 35382456, 2022). "Aberrantly expressed ISL1 has been reported in various cancers, including gastric cancer, non-Hodgkin lymphoma, neuroblastoma, breast cancer, OSCC, etc.." (PMID 35096593, 2021). "Regulatory elements controlling ASCL1 expression are bound by LMO1, MYCN and the transcription factors GATA3, HAND2, PHOX2B, TBX2 and ISL1—all members of the adrenergic (ADRN) neuroblastoma core regulatory circuitry (CRC)." (PMID 31819055, 2019). "Our study revealed a temporal requirement for ISL1 in multiple aspects of sympathetic neuron development, and suggested Isl1 as a candidate gene for neuroblastoma." (PMID 29445148, 2018). "ISL1 is overexpressed in most types of neuroblastoma, particularly in poorly differentiated neuroblastomas that indicates a poor prognosis." (PMID 29445148, 2018). "We identified 88 transcription factors, many of which have been described previously as part of the core regulatory transcription factor circuitry in specific cancer types, such as PHOX2B, TWIST1, and ISL1 in neuroblastoma; MYOD1 and MYOG in rhabdomyosarcoma; NR0B1 in Ewing sarcoma." (PMID 34818552, 2021). "In addition, Isl1 functions as a marker for well-differentiated pancreatic neuroendocrine tumors, rhabdomyosarcoma, and neuroendocrine tumors and also facilitates neuroblastoma development." (PMID 37667288, 2023). "The adrenergic CRC consists of an interdependent autoregulatory network that includes HAND2, ISL1, PHOX2B, GATA3, ASCL1, and TBX2 and is essential to drive the expression of MYCN and to facilitate the growth and survival of MYCN-amplified neuroblastoma cells." (PMID 34669465, 2021). "Gene expression levels for the adrenergic neuroblastoma CRC members—MYCN, HAND2, ISL1, PHOX2B, GATA3, ASCL1, and TBX2—were assayed by quantitative RT-PCR at 1, 3, and 6 days after treatment with 5 μM ATRA." (PMID 34669465, 2021). "A set of six markers (CCND1, DDC, GABRB3, ISL1, KIF1A, PHOX2B) was identified by genome-wide gene expression microarray analyses of 48 neuroblastoma tumors and nine remission BM samples followed by selecting genes with higher tumor-to-BM expression ratios." (PMID 31214500, 2019). "However, the role of ISL1 in neuroblastoma tumorigenesis is unknown." (PMID 29445148, 2018). "Neuroblastoma derives from embryonic neural crest cells, and in NB tumors that harbor amplification of the proto-oncogene MYCN, a transcriptional core regulatory circuitry (CRC) that includes MYCN, HAND2, ISL1, PHOX2B, GATA3, and TBX2 promotes tumorigenesis." (PMID 40766465, 2025). "Furthermore, expression of several genes associated with glioblastoma (STAT3, PDGFRA, MET, and NF1) and neuroblastoma (GATA3, ISL1, LMO1, and LIN28B) progression was downregulated at the transcriptional level in differentiated cells." (PMID 39859209, 2025).
neuroblastoma (continued). "Thus, ATRA initiates a change in cell state of neuroblastoma cells corresponding to a shift from the adrenergic CRC to a new retino-sympathetic CRC, which includes RARA, HAND2, ISL1, TBX2, TBX3, MEIS1, and SOX4." (PMID 34669465, 2021). "This variant was found to be located in open chromatin regions identified in 29 ATAC‐seq and 5 H3K27ac ChIP‐seq experiments in various neuroblastoma cell lines, but also showed the highest enrichment of TF binding sites, including MYCN, LMO1, GATA3, HAND2, ISL1, PHOX2B, and TBX2." (PMID 40525640, 2025). "Indeed, MYCN, ISL1, HAND2, and PHOX2B, together with GATA3 and TBX2, comprise the core regulatory circuit, an autoregulatory transcriptional loop that maintains the malignant phenotype of MYCN-positive neuroblastoma." (PMID 37297004, 2023).
gastric cancer (14 papers, 2016 to 2024). A primary or metastatic malignant neoplasm involving the stomach. "High expression of ISL1 is also associated with the depth of tumour invasion, lymph node metastasis, the histological grade of the tumour and poor survival in gastric cancer patients." (PMID 32158343, 2020). "Here, we report that ISL1 is aberrantly upregulated not only in human gastric carcinoma tissues but also in some GC cell lines." (PMID 27183908, 2016). "Upregulated ISL1 expression enhanced xenografted gastric carcinoma development, while ISL1 knockdown inhibited GC growth in nude mice." (PMID 27183908, 2016). "Moreover, the phosphorylation of ISL-1 via the activity of CDK1 stabilizes ISL-1 in gastric cancer cells." (PMID 36769170, 2023). "ISL1 may be a potential prognostic marker of gastric cancer." (PMID 35096975, 2021). "Besides, ISL1 was also verified to be a novel regulator of the cyclin D1 and c-Myc genes in cancer, and it could predict prognostics for cancers like gastric cancer, bladder cancer, and may also act as a biomarker in NB." (PMID 34131100, 2021). "However, the function and underlying mechanisms of ISL1 in gastric cancer (GC) have not been fully elucidated." (PMID 30674889, 2019). "A transcription factor named Islet-1 (ISL-1), containing a LIM-home domain, is known to function in the progression of gastric cancer." (PMID 36769170, 2023). "ISL1 expression was recently found to show significant correlation with the depth of tumour invasion, lymph node metastasis and TNM stage of gastric cancer." (PMID 32158343, 2020). "Previously, we reported that ISL1 is aberrantly overexpressed in gastric cancer (GC)." (PMID 27183908, 2016). "ISL1 serves as a novel regulator for the expression of CCNB1, CCNB2 and C-MYC, which plays significant roles in gastric cancer progression and development." (PMID 27835911, 2016). "ISL1 was involved in triple-negative breast cancer, melanoma, and gastric cancer progression, and it was highly expressed in non-Hodgkin lymphoma compared to normal lymph nodes or Hodgkin lymphoma." (PMID 34131100, 2021).
breast carcinoma (12 papers, 2014 to 2022). "DNMT1 inhibition or DNMT1 induced Islet-1 (ISL1) hypermethylation/down-regulation limits the number of CSCs in breast cancer cells." (PMID 33616161, 2021). "DNMT1 promotes hypermethylation and downregulation of tumor suppressor gene ISL1 which increases the tumor stem cell population in breast cancer cells." (PMID 31828117, 2019). "OCT4 is dependent on ERα to suppress the proliferation of breast cancer cells through DNMT1/ISL1/ERK axis." (PMID 31012189, 2019). "Next, we evaluated ISL1 expression in 10 samples of normal breast tissues and 66 samples of different subtypes of breast cancer tissues." (PMID 31012189, 2019). "Our current work shows that OCT4 requires ERα to suppress the proliferation of breast cancer cells through the DNMT1/ISL1/ERK axis, providing a novel molecular circuit for inhibiting BCC proliferation." (PMID 31012189, 2019). "Immunohistochemical staining for ER, PR, HER-2, Ki-67, 5-meC, DNMT1, and ISL-1 were performed on 348 breast cancer samples in tissue microarray." (PMID 27071379, 2016). "We assessed the expression of methylation-related proteins 5-meC, DNMT1, and ISL-1 in breast cancer and evaluated their relationship to clinicopathological factors." (PMID 27071379, 2016). "We assessed the expression of methylation-related proteins 5-meC, DNMT1, and ISL-1 in breast cancer and evaluated their relationships with clinicopathological factors." (PMID 27071379, 2016). "Among these, ISL-1 was reported to drive gastric and breast cancer progression." (PMID 36583015, 2022). "Thus, for the first time, we demonstrate that OCT4 is dependent on ERα expression to suppress proliferation in ERα‐positive breast cancer cells through the regulation of DNMT1/ISL1 and the inactivation of ERK signalling pathway." (PMID 31012189, 2019). "DNMT inhibition or ISL1 expression in breast cancer cells limits CSC population." (PMID 30674889, 2019). "Interestingly, ISL1, as a direct DNMT1 target, hypermethylated and downregulated in mammary tumors and CSCs." (PMID 30674889, 2019). "In addition, the LIM (Lin11, Isl-1, and Mec-3) domain-containing protein LMO4 (LIM-only protein 4) is highly expressed in breast cancer, and its aberrant expression leads to centrosome amplification and defects in spindle formation." (PMID 26893288, 2016). "It was further revealed that lower ISL1 transcript expression was significantly correlated with poorer survival in breast cancer patients (p < 0.05); however, it was not demonstrated whether DNMT1 expression was inversely correlated in breast cancer patients." (PMID 34360879, 2021).
myocardial infarction (12 papers, 2012 to 2025). Gross necrosis of the myocardium, as a result of interruption of the blood supply to the area, as in coronary thrombosis. "GATA5/ISL1 promotes this conversion by inhibiting Wnt/β-catenin signaling, ultimately improving cardiac structure and function in mice after myocardial infarction." (PMID 41403700, 2025). "Conversely, using CRISPRa to activate specific genetic programs in GATA5/ISL1+ fibroblasts promoted cardiac repair and improved function after myocardial infarction." (PMID 41403700, 2025). "It has been reported that ISL1 overexpression in human MSCs promoted cell survival and improved cardiac function in the model of myocardial infarction." (PMID 39066917, 2024). "Our studies demonstrated that transplantation of small intestinal submucosa seeded with Isl1+ cardiac progenitor cells significantly alleviated myocardial damage and improved cardiac function following myocardial infarction in mice." (PMID 29037258, 2017). "Our study demonstrates global and focal up-regulations of c-Kit and Isl1, respectively, as well as Nkx2.5, after ischemia-reperfusion injury but also after myocardial infarction and pregnancy." (PMID 22590612, 2012). "Based on the quantitative RNA analysis from the different groups, ischemia-reperfusion injury (IR and IR+GF) induced a stronger up-regulation of c-Kit, Isl1 and Nkx2.5 versus the control group than both myocardial infarction and pregnancy." (PMID 22590612, 2012). "Ischemia-reperfusion injury induced a robust up-regulation of Isl1 expression compared to myocardial infarction." (PMID 22590612, 2012). "In contrast to the c-Kit response, the up-regulation of Isl1 as a response to ischemia-reperfusion and myocardial infarction was mainly located in the outflow tract area, but also in the remote areas of the left ventricle and peri-ischemic regions." (PMID 22590612, 2012). "ISL1+ MESP1+ FOXA2+ stem cell clones isolated from neonatal cardiovascular tissue represent a novel resource of cells with the capacity to restore cardiac function following myocardial infarction in a preclinical large animal model." (PMID 41561127, 2025). "Besides, ISL1 overexpression MSCs and their derived exosomes have been shown to promote angiogenesis and protect endothelial cells in the myocardial infarction model." (PMID 39066917, 2024). "This study investigated whether forced expression of ISL1 in human mesenchymal stem cells (hMSCs) improves myocardial infarction (MI) treatment outcomes." (PMID 29482621, 2018). "For example, overexpression of islet-1 (ISL1) enhanced the paracrine effect of MSCs and promoted angiogenesis in a myocardial infarction model." (PMID 38791243, 2024). "The functions of the transcription factors islet-1 (ISL1) and platelet fibrin (PRF) in regulating the repair of myocardial infarction by MSCs have been explored." (PMID 33239082, 2020). "Mice from the reporter mouse line Isl1‐nLacZ were primed with TB4 and subsequently underwent myocardial infarction." (PMID 29864245, 2018). "Comparable ISL1+ MESP1+ FOXA2+ stem cell clones were then isolated from sheep for functional analysis in a sheep model of myocardial infarction and allogeneic stem cell-based repair without immunosuppression." (PMID 41561127, 2025). "We compared the functional outcome of Isl-1+ cardiac progenitors, CD90+ bone marrow-derived progenitor cells, and the combination of the two in a rat myocardial infarction (MI) model." (PMID 31781239, 2019). "Contrary to c-Kit, Isl1 was not up-regulated by pregnancy or myocardial infarction while ischemia-reperfusion injury induced not a global but a focal up-regulation in the outflow tract and also in the peri-ischemic region, correlating with the up-regulation of endogenous IGF-1." (PMID 22590612, 2012).
pancreatic neuroendocrine tumor (10 papers, 2014 to 2024). Pancreatic endocrine tumor, also known as pancreatic neuroendocrine tumor (PNET), describes a group of endocrine tumors originating in the pancreas that are usually indolent and benign, but may have the potential to be malignant. "CDX2 is also expressed in around 15% of pancreatic NETs with co-expression of pancreatic markers such as Islet 1 (ISL1) and PAX-6/8." (PMID 35626118, 2022). "A study on pancreatic endocrine tumour also showed significant correlation between ISL1 expression and tumour metastasis." (PMID 32158343, 2020). "More recently, the expression pattern of CDX-2, PAX-6, ISL-1, ER, and PR in the GI and pancreatic NET was investigated and showed small differences between the primary and metastatic NETs." (PMID 29713473, 2018). "ISL1 plays an important role in a variety of cellular processes, including cytoskeleton genesis, organogenesis, and tumorigenesis, and has been found to be a highly specific marker for pancreatic endocrine tumors and metastases." (PMID 34368227, 2021). "For lung NETs, the 10% of midgut CDX 2-negative tumours, and the 5–10% of PAX6/ISL1 negative pancreatic NETs, other markers should be determined." (PMID 35626118, 2022).